ACTA2 (actin alpha 2, smooth muscle)
Diseases named in the same sentence as ACTA2 in open-access papers (continued):
Sharing a sentence is not in itself a finding about the gene and the disease.
Glomerular sclerosis (1 paper, 2020). Accumulation of scar tissue within the glomerulus. "Furthermore, SFN treatment (5/6NX + HA + SFN group) significantly reduced the fibrosis area, glomerular sclerosis index, and fibrotic protein levels (COL1A1, VIM, and ACTA2) compared with those in the 5/6NX + HA group." (PMID 32854194, 2020).
hemangioma (1 paper, 2022). A benign vascular lesion characterized by the formation of capillary-sized or cavernous vascular channels. "Immunohistochemical overexpression of smooth muscle actin (encoded by the ACTA2 gene) in hemangioma cells, mainly in sclerosing lesions, has been very rarely reported in the literature in human tissues." (PMID 35740845, 2022). "Preliminary data support ACTA2 upregulation as one of the mechanisms of hemangioma involution, but more research is needed to determine its role in hemangioma regression." (PMID 35740845, 2022). "No data about ACTA2 gene upregulation nor its association with involuting hemangioma has been reported before the present study." (PMID 35740845, 2022). "AKT1, p38/MAPK14 (upregulated in proliferating hemangioma but downregulated in involuting hemangioma), and ACTA2 (upregulated in involuting hemangioma but downregulated in proliferating hemangioma) were found to have divergent expression in proliferating and involuting hemangiomas." (PMID 35740845, 2022). "Proliferating hemangioma had MAPK14 and AKT1 gene upregulation and ACTA2 downregulation." (PMID 35740845, 2022).
Hepatitis (1 paper, 2016). Inflammation of the liver. "In addition, ACTA2 is a marker of hepatitis stellate cells and correlated significantly with necroinflammatory grades and fibrotic stages in CHB or CHC." (PMID 28025641, 2016).
hydronephrosis (1 paper, 2020). Collection of urine in the renal pelvis that results in dilatation of the renal pelvis and calyces. "However, here, we reported a prenatal case characterized by ultrasound abnormalities including oligohydramnion, bilateral echogenic kidneys, bilateral hydronephrosis, megalo‐ureter, and megabladder, and this distinct case presented a novel prenatal form of variants in ACTA2 (p.R179H)." (PMID 32779812, 2020).
Hyperinsulinemia (1 paper, 2022). An increased concentration of insulin in the blood. "Hyperinsulinemia treatment led to a significant downregulation of ACTA2 gene expression in VIC under NG (p = 0.016) as well as under HG conditions (p = 0.047) compared to NG control conditions." (PMID 36386326, 2022).
in situ ductal carcinoma (1 paper, 2023). "Reduced MEC differentiation measured by a decrease in expression of Cnn1 and Acta2 also precedes the progression of in situ ductal carcinoma to invasive disease in mammary gland; thus, the clinical impact of targeting MEC differentiation may expand beyond SG regeneration." (PMID 36966175, 2023).
infantile hemangiomas (1 paper, 2022). "Involuting infantile hemangioma was characterized by ACTA2 upregulation and AKT1 and MAPK14 downregulation." (PMID 35740845, 2022). "Three genes, AKT1, p38/MAPK14, and ACTA2, were found to have divergent expression in proliferating and involuting infantile hemangiomas." (PMID 35740845, 2022). "In our study, involuting infantile hemangioma was characterized by downregulation of p38/MAPK14 and upregulation of the ACTA2 gene." (PMID 35740845, 2022).
intracranial aneurysms (1 paper, 2024). "In addition to cardiovascular disorders, pathogenic variants of the ACTA-2 gene predispose patients to other forms of vascular pathologies, including Moyamoya-like occlusions that can lead to early onset of cerebrovascular events or occlusions of internal carotid arteries or intracranial aneurysms." (PMID 39685614, 2024).
keratoconus (1 paper, 2009). A degenerative, structural disorder of the eye, characterized by a cone-shaped protrusion of the cornea. "Meanwhile, ACTA2, which has been known to be involved in the cytoskeleton, showed low expression in keratoconus." (PMID 19956410, 2009). "The underexpression of genes such as ACTA2 and GRCC10 in keratoconus was believed to delay the growth of keratocytes that were necessary for the synthesis and maintenance of collagen fibrils and the extracellular matrix." (PMID 19956410, 2009). "However, we assessed the expression of eight genes in more detail by employing RT-PCR and real-time PCR, which confirmed the overexpression of BMP4, CFL1, and MRVI1, and the underexpression of ACTA2, GRCC10, TIMP3, TIMP1, and SSTR1 in keratoconus." (PMID 19956410, 2009).
kidney cancer (1 paper, 2023). Primary or metastatic malignant neoplasm involving the kidney. "In kidney cancer cells, Pten knockout caused changes in epithelial to mesenchymal transition marker expression, with downregulation of E-cadherin and upregulation of Snail, Mmp9, and Acta2 (α-SMA)." (PMID 37673853, 2023).
Klinefelter syndrome (1 paper, 2025). A sex chromosome disorder caused by the presence of an extra X chromosome in the male karyotype. "Adult Klinefelter syndrome participants, for example, also typically possess low T levels and exhibit an ‘interrupted’ or ‘absent’ ACTA2 pattern." (PMID 39773877, 2025).
lactic acidosis (1 paper, 2023). Metabolic acidosis characterized by the accumulation of lactate in the body. "On the contrary, lactic acidosis increased the expression levels of typical myofibroblast-related genes, such as ACTA2 (i.e., gene encoding α-SMA), COL1A1, and COL1A2, which were 2.5-fold, 3-fold, and 4-fold increased, respectively, compared to the basal conditions." (PMID 36980280, 2023).
left ventricular hypertrophy (1 paper, 2024). Enlargement of the LEFT VENTRICLE of the heart. "This makes it unlikely that excessive left ventricular hypertrophy triggers the observed changes in endothelin-1 and ACTA2 in the lungs." (PMID 39452062, 2024).
leukoaraiosis (1 paper, 2015). "The MRI T2-weighted hyperintensities in the periventricular white matter (leukoaraiosis) have been previously observed in ACTA2 patients with R179 mutations but the histopathologic basis has not been clearly defined." (PMID 26637293, 2015).
lymphedema (1 paper, 2022). Excess fluid collection in tissues, causing swelling. "However, the overall analysis showed that lymphedema increases the mRNA expression of type I and type III collagen, connective tissue growth factor (CTGF), ACTA‐2, FN‐1 and MMP‐9." (PMID 35652284, 2022).
mesenchymal tumours (1 paper, 2022). "Fibroblasts from epithelial tumours contained more miR‐200 and expressed less ACTA2 and FN1 than those from mesenchymal tumours." (PMID 35595718, 2022).
metastasis (1 paper, 2018). The spread or migration of cancer cells from one part of the body (where they first appeared) to another. "In the RNA sequencing data genes linked to arteries (Elastin, Lamb1, Acta2), pericytes (Cspg4/Ng2, Pdgfrb, Sca1 (Ly6a)) and neurons/neurites (Gap43, Tubb3) were up-regulated in the stroma of osteolytic bone metastasis." (PMID 29988965, 2018).
metastatic tumors (1 paper, 2017). "We observed that ACTA2 protein expression significantly decreased in ACTA2-knockdown lung metastatic tumors when compared with control lung metastatic tumors." (PMID 28881584, 2017).
Miscarriage (1 paper, 2019). A pregnancy that ends at a stage in which the fetus is incapable of surviving on its own, defined as the spontaneous loss of a fetus before the 22th week of pregnancy. "Moreover, a number of genes identified have been implicated in miscarriage (Fgl2) and in the development of placental dysfunction in the pregnancy complication, preeclampsia (Acta2, Ngf and Nov/Ccn3)." (PMID 31241463, 2019).
myocardial ischemia (1 paper, 2021). A disorder of cardiac function caused by insufficient blood flow to the muscle tissue of the heart. "Morphological observation and expression of the fibrotic genes COL1A1 (Col1) and ACTA2 (αSMA) were used to validate myocardial ischemia." (PMID 32845445, 2021).
myopia (1 paper, 2025). "Additionally, the involvement of fibrosis-related markers like ACTA2 (α-SMA) highlights the potential pathways by which atropine could influence scleral stiffness and myopia progression." (PMID 40183102, 2025).
neurofibromatosis type 1 (1 paper, 2026). A clinically heterogeneous, neurocutaneous genetic disorder characterized by cafe-au-lait spots, iris Lisch nodules, axillary and inguinal freckling, and multiple neurofibromas. "We analyze the role of genes involved in vascular smooth muscle cell contractility (ACTA2, MYH11), TGF-β signaling, and DNA repair mechanisms that drive MMS, alongside the genetic basis of syndromic forms associated with neurofibromatosis type 1, trisomy 21, and RASopathies." (PMID 42196405, 2026).
osteoarthritis (1 paper, 2022). A noninflammatory degenerative joint disease occurring chiefly in older persons, characterized by degeneration of the articular cartilage, hypertrophy of bone at the margins and changes in the synovial membrane. "Mean follow-up duration for the group was 16.4 years (range 0.2–30 years) and 74 individuals died during follow-up (Marfan = 52, Loeys-Dietz = 6, aneurysm-osteoarthritis = 4, ACTA2 aneurysm = 1, heritable non-syndromal aortopathy = 11)." (PMID 36312254, 2022).
ovarian tumors (1 paper, 2016). "Transcript levels of ACTA2 (the gene encoding αSMA) and FAP were significantly higher in SPHK1-High tumors than in SPHK1-Low tumors in both the AOCS and TCGA datasets, suggesting that SPHK1 could be associated with an increased abundance of CAFs in ovarian tumors." (PMID 26716409, 2016).
Peritoneal Fibrosis (1 paper, 2023). Disorder characterized by a wide range of structural changes in PERITONEUM, resulting from fibrogenic or inflammatory processes. "In TGF-β1-stimulated HPFBs, pro-fibrotic genes (COL1A1, COL1A2, ACTA2, CTGF, FN1, and TGFB1) exhibited higher expression than in controls, which are crucial targets of sildenafil and SB204741 against peritoneal fibrosis." (PMID 38322704, 2023).
pneumococcal infection (1 paper, 2014). Infections with bacteria of the species streptococcus pneumoniae. "Furthermore, we found that during pneumococcal infection the expression of genes known to regulate transcription of Acta2 differed significantly between resistant and susceptible mice." (PMID 24594938, 2014).
Pulmonary hemorrhage (1 paper, 2024). Pulmonary hemorrhage is a bleeding within the lungs. "We present a 15-year-old boy with a heterozygous pathogenic variant in ACTA2 who presented with right brachial artery aneurysm thrombosis treated initially with tPA, resulting in pulmonary hemorrhage." (PMID 39310919, 2024). "We hypothesize that the underlying pulmonary abnormalities caused by the pathogenic ACTA2 variant may be a risk factor for pulmonary hemorrhage after tPA administration." (PMID 39310919, 2024).
pyelonephritis (1 paper, 2020). An inflammatory process affecting the kidney. "In comparison, our pyelonephritis model features regional injury and scarring that is comparatively limited in scope; as a result, analysis of our whole‐kidney homogenates did not reveal increased Col1A1 (collagen I) and Acta2 (α‐smooth muscle actin) transcription in TC‐treated mice." (PMID 32227630, 2020).
renal angiomyolipoma (1 paper, 2021). "Among the genes upregulated in the TSC2−/− organoids were: MLANA, PMEL, GPNMB, CTSK, and ACTA2, with median expression fold change 121x-, 88x-, 34x-, 14x-, 9.5x, respectively, all of which are known to be highly expressed in the renal angiomyolipoma." (PMID 34764250, 2021).
renal carcinoma (1 paper, 2021). A carcinoma arising from the epithelium of the renal parenchyma or the renal pelvis. "For example, expression of ACTA2 is universal in cancers, and used as a poor prognostic marker in renal cancer." (PMID 33468253, 2021).
S. pneumoniae pneumonia (1 paper, 2019). "We found that neonatal S. pneumoniae pneumonia upregulated airway Acta2 and Myh11 mRNAs and α-SMA and SMMHC proteins in the adulthood mice and also promoted AHR." (PMID 30723734, 2019). "The expression of smooth muscle-specific genes (actin-α2-smooth-muscle-aorta, Acta2 and myosin-heavy-chain-11-smooth-muscle, Myh11, respectively) was remarkably increased in neonatal S. pneumoniae pneumonia group, consistent with the Western blotting and histologic results." (PMID 30723734, 2019).
sarcoma (1 paper, 2025). A usually aggressive malignant neoplasm of the soft tissue or bone. "Smooth muscle actin, encoded by ACTA2, was expressed in all 10 PLMS cases but only in 11 of 17 other high-grade sarcomas." (PMID 40868997, 2025).
skin changes (1 paper, 2024). "The gene sets encompass numerous genes previously implicated in the pathogenesis of SSc, such as Acta2, Col1a1, Col3a1, Smad3, Ctgf, Msr1, Cd4, Cd8a and Cd68, supporting the potential of anti-PRMT5 in induction of SSc-like skin changes." (PMID 38684324, 2024).
synucleinopathy (1 paper, 2025). A neurodegenerative disease that is characterized by the abnormal accumulation of aggregates of alpha-synuclein protein in neurons, nerve fibers or glial cells. "Instead, we demonstrated the suppression of other microglial mobility/phagocytosis-associated genes such as Icam2, Acta2, Fos, Fosb, Egr1, Lamb2 and Tpm2 in both synucleinopathy patients and the animal model." (PMID 41258081, 2025).
systemic sclerosis (1 paper, 2021). A chronic disorder, possibly autoimmune, marked by excessive production of collagen which results in hardening and thickening of body tissues. "AKT1 is reported to be a strong regulator of ACTA2 in fibroblasts freshly isolated from skin with systemic sclerosis." (PMID 33799788, 2021).
tendinopathy (1 paper, 2017). "After SP treatment in our cultured healthy cells, levels of COL3A1, MMP1, and ACTA2 genes were increased, which were also shown in the tendinopathy samples." (PMID 28598390, 2017). "Therefore, an increase in ACTA2 expression, along with increased α-smooth muscle actin production in myofibroblasts, is one of the hallmarks of tendinopathy lesions." (PMID 28598390, 2017). "The results showed that tendinopathy tenocytes had higher levels of COL3A1, MMP1, COX2, SCX, ACTA2, and substance P gene expression compared to healthy tenocytes." (PMID 28598390, 2017). "As shown in the results comparing the healthy and tendinopathy samples, the relative mRNA expressions of COL3A1, COX2, SCX, MMP1, and ACTA2 were increased by 1.4, 1.8, 2.7, 1.3, and 1.6 times in the SP-treated samples compared to the PBS-controls (p < 0.05 in all), respectively." (PMID 28598390, 2017).
thyroid-associated ophthalmopathy (1 paper, 2020). "On the other hand, IL-17A promoted ACTA2 expression in orbital fibroblasts in thyroid-associated ophthalmopathy." (PMID 32670268, 2020).
transient ischemic attack (1 paper, 2023). A brief attack (from a few minutes to an hour) of cerebral dysfunction of vascular origin, with no persistent neurological deficit. "MMA patients typically present with transient ischemic attacks (TIA) during the juvenile stage of MMA, suggesting that TAAD associated with ACTA2 mutations may not be characteristic for MMA." (PMID 37273690, 2023).
ulcer (1 paper, 2017). "Relative ulcer volume (RUV) was measured every month; biopsies were taken at baseline and months 1 and 2 for histopathology and gene expression analysis for COL-1α, COL-4, KGF, VEGF, ACTA2 (α-SMA), elastin, fibronectin, TGF-β1, TGF-β3, HIF-1α, and HIF-1β." (PMID 29675430, 2017).
Venous malformation (1 paper, 2021). A vascular malformation resulting from a developmental error of venous tissue composed of dysmorphic channels lined by flattened endothelium and exhibiting slow turnover. "qPCR was used to detect the expression of ACTA2 in pathological tissues of patients with venous malformation and control tissues." (PMID 34858981, 2021). "The differentially expressed gene ACTA2 was identified and validated in the tissues of patients with venous malformations by RNA and protein expression profiles." (PMID 34858981, 2021). "Compared with healthy people, the expression of ACTA2 was significantly reduced in patients with venous malformations." (PMID 34858981, 2021). "Considering lower expression of ACTA2 in patients with venous malformation, we performed over-expression of ACTA2 in HMEC1 cells." (PMID 34858981, 2021). "ACTA2 may be a potential target for the diagnosis and treatment of disseminated venous malformations." (PMID 34858981, 2021). "ACTA2 can be used as a potential biomarker for the treatment and prognosis of venous malformations." (PMID 34858981, 2021). "In this study, the deletion of ACTA2 resulted in the disruption of HMEC proliferation, leading to a lack of vascular development and causing venous malformations." (PMID 34858981, 2021).
viral infections (1 paper, 2021). "PSAT1 and ACTA2 were up-regulated in response to all viral infections, with higher induction in cells infected with CHIKV and MAYV at 18 hpi." (PMID 33791243, 2021).